JUN (Jun proto-oncogene, AP-1 transcription factor subunit)
Diseases named in the same sentence as JUN in open-access papers (continued):
Sharing a sentence is not in itself a finding about the gene and the disease.
glioblastoma (40 papers, 2014 to 2025). The most malignant astrocytic tumor (WHO grade IV). "Overall, our results provide evidence that FKBP38 depletion induces autophagy through the JNK/c-JUN–PTEN–AKT axis in human glioblastoma neurospheres." (PMID 37947640, 2023). "Overall, these data suggest that the elevated activity of JUN is positively correlated with MES‐subtype of pathological features in human glioblastoma." (PMID 35851726, 2022). "ATF3 and c-JUN act downstream of GADD45α to mediate the stress-related pathway in glioblastoma cells." (PMID 31541175, 2019). "ADM is reported to induce the phosphorylation of c-JUN in glioblastoma cells, but is also a candidate target of c-JUN in our prediction." (PMID 24912499, 2014). "Furthermore, this autophagic cascade was found to be the result of the activation of the JNK/c-JUN–PTEN–AKT axis in human glioblastoma neurospheres." (PMID 37947640, 2023). "Therefore, JUN transcription regulatory network is necessary to remodel chromatin accessibility and thereby promotes glioblastoma progression, which will hopefully provide a novel targeting therapeutic strategy." (PMID 35851726, 2022). "In conclusion, this study demonstrates that activated JUN is necessary and sufficient to remodel chromatin accessibility and trigger the activation of mesenchymal subtype‐specific transcription regulatory network, and thereby promotes glioblastoma progression." (PMID 35851726, 2022). "Some specific pathways containing MELK have been identified in glioblastoma multiforme (GBM), such as the c-JUN/MELK and MELK/PRC1 cascades, which support the survival of cancer stem cells (CSCs)." (PMID 31861475, 2019). "Moreover, upon JUN, CEBPB and HDAC3 knockdown, the expression levels of MGMT decreased significantly, suggesting that these genes could regulate drug resistance of glioblastoma by mediating MGMT status." (PMID 30775317, 2019). "Stress-inducible genes, such as GADD45α/β, ATF3, and c-JUN, which were remarkably upregulated in PAM-treated glioblastoma cells, were not upregulated by PAL." (PMID 31541175, 2019).
leukemia (39 papers, 2011 to 2024). A malignant (clonal) hematologic disorder, involving hematopoietic stem cells and characterized by the presence of primitive or atypical myeloid or lymphoid cells in the bone marrow and the blood. "This illustrated that the leukemia-supportive LYN effects in BMSC were at least partially mediated by c-JUN." (PMID 36899005, 2023). "ScRNA-seq reveals an expression pattern with high FOS and JUN at leukaemia evolution, which resolves following therapy but reoccurs following relapse and death." (PMID 33441952, 2021). "In leukemia, EGR-1 has been implicated in the apoptosis of myeloma cells via interaction with c-JUN while it behaves as a tumor suppressor against the oncogenes E2F-1 and c-MYC." (PMID 22461839, 2012). "In a model of murine leukemia, c-JUN prevents the epigenetic silencing of the cell cycle kinase CDK6." (PMID 21789792, 2011). "c-JUN may act as an additional TF that lies at the intersection of EG and leukemia and may enhance the development of leukemia along with skewing of the EG response." (PMID 29593731, 2018). "Most of the genes in the HIF1A module play leukemia-promoting roles in AML, such as HIF1A, CEBPG, JUN, and ATF4." (PMID 37691822, 2023). "Rothem et al26 have reported that reduced expression of transcription factors as CREB1, ATF1, USF1, FOS, JUN, Sp3, and Sp1 is responsible for a major decrease in RFC mRNA expression in the CCRF‐CEM and derived human leukemia cell lines." (PMID 32614991, 2020). "JUN (c-JUN) is induced upon RUNX1/ETO expression, and it scored in the in vivo RNAi screen as being essential for leukemia propagation." (PMID 30300583, 2018). "BATF or JUN mediated enhanced leukemia clearance in our model independent of starting cell state, indicating that these TFs may derive most of their early in vivo activity via binding to NFAT-AP1 composite motifs, which show high accessibility in both cell types." (PMID 38196657, 2023).
viral infection (38 papers, 2010 to 2025). "FOS and JUN are early response genes whose expression is induced by cell-extrinsic and cell-intrinsic signals like during viral infection." (PMID 35854219, 2022). "Because the known targets of c-JUN as well as Jun itself display high expression fold changes, we infer that viral infection to HeLa cells strongly increases the activity of c-JUN." (PMID 24912499, 2014). "Similarly, SP1 and JUN have been shown to function together to induce TNF expression in response to viral infection and SPI1 has been shown to promote IL10 expression —a cytokine often seen to be dysregulated in autoimmune diseases as in PR3+ AAV." (PMID 36768148, 2023). "Besides, we also found several instances including differentially expressed C4B gene and SMAD3/SMAD4/JUN/FOX complex to explore potential possible mechanistic details of how non-tumor individuals who are not susceptible fend off viral infections." (PMID 38752789, 2024). "In the context of viral infections, HCV enhances the phosphorylation of JUN and FOS by upregulating the double-stranded RNA-activated protein kinase R (PKR), promoting viral replication." (PMID 40005815, 2025). "At the early stages of virus infection i.e. at 4 hpi, we found up-regulation of immune genes like TNF-α3, EGR-1, IL6R, v-FOS, v-JUN." (PMID 21439068, 2011). "It was first reported that human IFN-β gene expression after virus infection requires the assembly of an enhanceosome, which includes four groups of transcription factors, the high mobility group protein HMGI, ATF2/c-JUN, NF-κB, and interferon response factors (IRFs), respectively." (PMID 41427291, 2025). "As a result, we hypothesized that JUN, VEGFA, TNFSF10, and TLR4 in PBMC can also regulate virus infection of HCC patients." (PMID 31531018, 2019). "EGRs, FOS and JUN are immediate early response genes which expression can be rapidly induced without requiring de novo protein synthesis during viral infection." (PMID 31725732, 2019). "Similarly, stress response and apoptosis-related genes FOS, JUN, and activating transcription factor 3 (ATF3) show increased expression in severe cases, highlighting the role of NK cells in modulating cell death pathways in response to viral infection." (PMID 39928675, 2025).
bladder cancer (37 papers, 2013 to 2026). "The TF-protein JUN (a regulator of ANGPT1, HPGD, ATF6B and OAS3) is associated with bladder cancer disease." (PMID 35617355, 2022). "The strong responsiveness of MMP1 to EGF relies on STAT3 phosphorylation and its interaction with c-JUN, and with this crucial activation of STAT3, T24 cells exhibit malignant characteristics in bladder cancer." (PMID 38320998, 2024). "After treatment of UMUC3 and T24T bladder cancer cells with ISO, sestrin 2 expression was elevated by activation of the MAPK8/JUN pathway, and activated sestrin 2 induced autophagy and inhibited the growth of bladder cancer cells." (PMID 34784907, 2021). "In bladder cancer cells, PDCD4 overexpression enhances sensitivity to cisplatin via regulation of the JNK/c-JUN pathway." (PMID 32260415, 2020). "Moreover, Sestrin2 is known to be downregulated in bladder cancer, and when Sestrin2 is induced in response to mitogen-activated protein kinase 8 (MAPK8)-JUN)-dependent transcription, it suppresses bladder cancer growth." (PMID 32882793, 2020).
psoriasis (36 papers, 2011 to 2025). An autoimmune condition characterized by red, well-delineated plaques with silvery scales that are usually on the extensor surfaces and scalp. "Another example of a daSNV that alters binding of the JUN TF is the psoriasis SNV rs10217259, which is looped to the KLF4 gene promoter." (PMID 40998781, 2025). "This signaling program resembles wound healing and psoriasis, and these pathways are well-described as oncogenic in specific contexts, predominantly c-JUN, IL6/JAK/STAT3, and TGFβ." (PMID 39358322, 2024). "For example, in the Tcm compartment, excluding mitochondrial and ribosomal transcripts, only KLRB1, IL17R, and JUN were expressed at greater than 0.5 logFC in psoriasis compared to normal samples." (PMID 35958578, 2022). "For example, SNP rs58726213 is associated with psoriasis and is ASB of CREB1 (reference allele preference, concordant with motif) and JUN (alternative allele preference)." (PMID 33980847, 2021). "Secondly, RELA, MAPKs, JUN, and BCL2L1 are associated with the aberrant biological behaviours of keratinocytes in psoriasis." (PMID 32655662, 2020). "In addition, during sepsis, adenosine promotes the expression of Foxp3 in Treg cells through JNK/AP-1 pathway, while JNK-phospho-c-JUN (ser63/73) pathway plays an important role in Foxp3 nuclear translocation in psoriasis." (PMID 36389828, 2022). "c-JUN activation could stimulate the production of inflammatory factor IL-6, thereby further aggravating the inflammatory response in psoriasis skin lesions." (PMID 35265149, 2022). "The differential expression of c‐JUN and JUNB in CD200+/K15+ bulge HF‐SCs in human samples of psoriatic plaques directed us to explore the potential causal contribution of epidermal stem cell populations to the initiation and development of psoriasis." (PMID 31556482, 2019). "Together with induction of AP1 members FOSB, FOSL1, JUN and JUNB, and EGR signalling, our data identify regulatory pathways induced by 311 nm UVB in psoriasis that control terminal differentiation of keratinocytes." (PMID 33812333, 2021).
nasopharyngeal carcinoma (33 papers, 2009 to 2026). A carcinoma arising from the nasopharyngeal epithelium. "Herein, we show that a JUN-mediated seRNA can form R-loop to regulate target genes to promote metastasis of nasopharyngeal carcinoma (NPC)." (PMID 37479693, 2023). "In that study, the authors found that the oncogene SPEN induces miR-4652-3p expression in nasopharyngeal carcinoma (NPC) by activation of the PI3K/AKT/c-JUN signaling and that miR-4652-3p targets and downregulates HIPK2." (PMID 36900356, 2023). "For example, inactivating mTOR by miR-3188 resulted in suppression of p-PI3K/p-AKT/c-JUN pathway, and mTOR in turn enhanced miR-3188 expression in nasopharyngeal carcinoma." (PMID 31315643, 2019). "We speculated that JUN may be participated in the regulation of nasopharyngeal carcinoma radiosensitivity through these pathways, the internal mechanism may need to be further tested in the future experiments." (PMID 31138194, 2019). "Therefore, we can infer that the up-regulated JUN may be a key node related with radioresistant nasopharyngeal carcinoma." (PMID 31138194, 2019). "For instance, Spen can regulate nasopharyngeal carcinoma (NPC) by maintaining the levels of PI3K/AKT and c-JUN." (PMID 41369415, 2025). "Another example is a JUN-mediated seRNA, associated with metastasis (seRNA-NPCM), which forms an R-loop to simultaneously regulate distal target (NDRG1) and neighbouring (TRIB1) genes to promote the metastasis of nasopharyngeal carcinoma (NPC)." (PMID 38542080, 2024). "Spen family transcriptional repressors activate PI3K/AKT signaling to modulate the c-JUN/miR-4652-3p/HIPK2 axis, thereby activating epithelial-mesenchymal transition signaling and promoting nasopharyngeal carcinoma metastasis." (PMID 37925170, 2023).
non-small cell lung carcinoma (29 papers, 2008 to 2026). A group of at least three distinct histological types of lung cancer, including non-small cell squamous cell carcinoma, adenocarcinoma, and large cell carcinoma. "Previous studies revealed that knockdown of PR55α hindered non-small cell lung cancer cellular growth by increasing JUN T239 phosphorylation." (PMID 33588847, 2021).
pulmonary fibrosis (29 papers, 2016 to 2025). Chronic progressive interstitial lung disorder characterized by the replacement of the lung tissue by connective tissue, leading to progressive dyspnea, respiratory failure, or right heart failure. "The elevated activities of the JUN pathway in fibroblasts revealed by phospho-c-JUN-specific antibodies implicated the involvement of JUN pathways in the progression of pulmonary fibrosis." (PMID 32493933, 2020). "Piezo1 is activated in response to cyclic pressure and drives c-JUN activation, endothelin-1 overexpression and HIF1α stabilization, facilitating the pro-inflammatory program in mouse lung fibrosis." (PMID 38267432, 2024). "Their analysis highlighted the expression of profibrotic genes DCN and JUN (C12 and C9, respectively): DCN modulates TGFβ‐driven fibrosis in a number of organs and JUN induction drives murine pulmonary fibrosis." (PMID 38685679, 2024). "As a member of the AP-1 family, JUN is an important transcription factor regulating cell growth and proliferation, and excessive activation of JUN can induce spontaneous pulmonary fibrosis." (PMID 37275876, 2023). "Recently, it has been found that the transcription factor JUN is highly expressed in pulmonary fibrosis, and its overexpression in mice can induce pulmonary fibrosis." (PMID 35132912, 2022). "Increased expression of CCL2, at least in the context of pulmonary fibrosis, is induced by NFκB (and AP-1 subunit c-JUN)." (PMID 35806457, 2022). "In summary, we demonstrated that immune-checkpoint CD47, PD-L1 and IL-6 signaling was markedly upregulated in a JUN-dependent fashion in pulmonary fibrosis patients and mouse lung-fibrosis models." (PMID 32493933, 2020). "Interestingly, we also have identified significant DEG-enrichments of target gene sets for five TFs, TCF12, ZEB1, NR3C1, TEAD4 and JUN, which were previously reported to be the regulators in idiopathic pulmonary fibrosis." (PMID 39103936, 2024). "The expression of JUN (coding for c-JUN) was increased in many human fibrotic diseases, and strong expression of FOSL2 (encoding FRA-2) was observed in human samples of pulmonary fibrosis associated with vascular remodeling." (PMID 36520540, 2023). "ATF2 regulates the expression of JUN through homo-dimerization or hetero-dimerization, consequently, might control pulmonary fibrosis." (PMID 34603282, 2021). "Therefore, the differential effects on lung fibrosis between JUN and FOS from this study in fibroblasts and the FOSL2 expression in mice macrophages illustrates the complexity of AP-1 family functions in lung fibrosis." (PMID 34972106, 2021). "The transcription factor JUN is highly expressed in pulmonary fibrosis." (PMID 32493933, 2020). "However, the molecular details of how JUN caused, or CD47 blockade disrupted, the development of lung fibrosis and the implications for human pulmonary fibrosis diseases remained unknown." (PMID 32493933, 2020). "Moreover, the activated phosphorylated form of JUN could represent a new biomarker to predict poor outcome in lung fibrosis." (PMID 32493933, 2020). "In summary, these studies have provided mechanistic insights into SARS-CoV-2-induced pulmonary fibrosis, revealing critical roles for the IFN-γ, IL-6/JUN/CD47, and TGF-β pathways, as well as identifying promising therapeutic targets, such as cytokine blockade, for treating PC19-PF." (PMID 40872813, 2025).
pulmonary fibrosis (continued). "By analyzing the target interaction network VCAM1,RELA,CDK2,JUN,CDK1,HSP90AA1,NOS2, SOD1,CASP3,AHSA1, PTGER3 are at the core of the network, which can be regarded as the key targets of Astragalus polysaccharides in treating pulmonary fibrosis." (PMID 35370663, 2022). "c-JUN is a component of the heterodimeric AP-1 transcription factor, which is regarded as an oncoprotein, and promotes fibrosis in liver, skin, and lung; a c-JUN N-terminal kinase (JNK) inhibitor has been used in clinical trials for patients with pulmonary fibrosis." (PMID 41100460, 2025).
Obesity (28 papers, 2015 to 2026). Accumulation of substantial excess body fat. "This c-JUN mediated cascade has also been discovered to be activated by increased metabolic stress caused by obesity." (PMID 37877121, 2023). "Obesity and hypertension share common susceptibility genes, such as genes Jun proto-oncogene (JUN), and serine/threonine kinase 1 (AKT1)." (PMID 37391689, 2023). "Increased expression of PDK1 and PDK2 by JUN and FOS enforces HIF1a stability to facilitate adipocyte differentiation and obesity." (PMID 34552205, 2021). "The most involved anti-obesity proteins include EGFR, STAT3, JUN, GSK3B, PPARG, and HSP90AA1." (PMID 38674532, 2024). "The NF-κB target genes JUN, PIK3R1, FOS, and IGF1R are enriched in the insulin signaling pathway which could contribute to obesity related disorders." (PMID 31013288, 2019). "The NF-κB target genes IRF1, STAT1, JUN, HSP90AA1, FOS, and EGR1, were enriched in the pathway of Glucocorticoid receptor regulatory network and homeostasis pointing towards their critical role in obesity." (PMID 31013288, 2019). "Interestingly, all tissues of T2D patients showed altered expression of genes involved in the inflammation response—such as SOCS1 in WB; CCL20 and SLAMF1 in SAT; ACP5, FOS, and JUN in VAT; and PLA2G2A in LT, showing the relevance of the systemic chronic inflammation in obesity and T2D." (PMID 29466957, 2018).